PICART1 (p53 inducible cancer associated RNA transcript 1)
Gene: Long non-coding RNA gene on chromosome 17 (50,050,349 to 50,056,018, reverse strand). Ensembl gene ENSG00000246640.
Diseases named in the same sentence as PICART1 in open-access papers:
PICART1 is named in the same sentence as 5 diseases in open-access papers, as found by Europe PMC text mining. Sharing a sentence is not in itself a finding about the gene and the disease. The quoted sentences say what the papers report.
lung carcinoma (2 papers, 2020 to 2022). "Among the five PRlncRNAs included in the signature, the lncRNA PICART1 is closely associated with the suppression of lung cancer cell proliferation by targeting the AKT1 and JAK2/STAT3 signaling pathways." (PMID 35739504, 2022).
chronic inflammatory demyelinating polyneuropathy (1 paper, 2021). "We investigated the expression levels of ANRIL, PICART1, MALAT1, CCAT1, CCAT2, and CCHE1 lncRNAs in acute and chronic inflammatory demyelinating polyneuropathy (AIDP and CIDP)." (PMID 33708228, 2021).
viral infections (1 paper, 2021). "Based on the importance of viral infections in the initiation of AIDP, the interplay between PICART1 and these two proteins might be implicated in the pathogenesis of this form of immune-related neuropathies." (PMID 33708228, 2021).
tumor (3 papers, 2021 to 2023).
PICART1 also shares sentences with these, for which no sentence is quoted: cancer (1 paper).